NLRP3 (NLR family pyrin domain containing 3)
Diseases named in the same sentence as NLRP3 in open-access papers (continued):
Sharing a sentence is not in itself a finding about the gene and the disease.
metabolic disorders (continued). "The literature has not fully explored the specific mechanisms of how fatty acids affect insulin signalling through the NLRP3 inflammasome, and how this effect may be linked to the development of metabolic disease." (PMID 39717099, 2024). "This implies that NLRP3 inflammasome inhibitors may have a broader therapeutic potential beyond metabolic disorders, extending to neurological conditions associated with neuroinflammation." (PMID 38732190, 2024). "Therefore, the in-depth study on the mechanism of NLRP3 inflammasome associated with metabolic disorders and kidney injury will provide new ideas and directions for the treatment of metabolic related kidney diseases." (PMID 34305953, 2021). "Moreover, activation of IL-1β in AD is linked to the NLRP3 inflammasome, and we have reported NLRP3 inflammasome formation and IL-1β activation in visceral adipose tissue and pancreas, known intermediaries of metabolic diseases." (PMID 33626069, 2021). "After activation, the NLRP3 inflammasome recognizes many types of dangerous molecules and pathogens and participates in the immune response, ultimately causing various immune or metabolic diseases." (PMID 34733156, 2021). "In this clinical context, the pharmacological blockade of TLR4 or the NLRP3/IL-1β/IL-1 receptor axis may provide a therapeutic strategy for preventing and/or treating the vascular alterations associated to metabolic diseases." (PMID 32214150, 2020). "Although the NLRP3 inflammasome is essential for host defense during infections, uncontrolled activation and overproduction of IL-1β and IL-18 increase the risk of developing autoimmune and metabolic disorders." (PMID 33101288, 2020). "In fact, pro‐inflammatory genes as TNF‐ɑ, IL‐1ɑ, IL‐1β, and NLRP3 are associated with a wide range of age‐related disorders, including cardiovascular, neurodegenerative, and metabolic diseases and the level of soluble TNF‐ɑ R1 was identified as a predictor of 10‐year all‐causes of mortality." (PMID 30488553, 2019). "Furthermore, NLRP3 inflammasome-mediated IL-1β has been identified as a key pathogenic cytokine that triggers and/or promotes various metabolic disorders." (PMID 30717382, 2019). "As NLRP3 activation is associated with many metabolic diseases that only develop later in life, NLRP3 blockade in older individuals may present more health benefits than risks." (PMID 27551512, 2016). "Despite the fact that deregulated NLRP3 inflammasome activation contributes to the pathogenesis of chronic inflammatory or metabolic disorders, the underlying mechanism by which NLRP3 inflammasome signaling is initiated or potentiated remains poorly understood." (PMID 26489382, 2015). "NLRP3 inflammasome formation promotes the proximity-induced autocatalytic activation of caspase-1 and mediates the cleavage/activation and secretion/release of the pro-inflammatory cytokines IL-1β and IL-18 implicated in several metabolic disorders." (PMID 23924318, 2013). "In addition to NOD1 and NOD2, NLRP3 activation is linked to more severe metabolic disease and bacterial peptidoglycan is a known activator of NLRP3, but experiments directly testing the impact of peptidoglycan on NLRP3-induced metabolic changes have not been reported and will require further study." (PMID 37128291, 2023). "The activation of the NLRP3 inflammasome can be triggered by diverse stimuli, including pathogen-associated molecular patterns (PAMPs) and damage-associated molecular patterns (DAMPs) generated from pathogens, environmental stresses, metabolic disorders, and tissue damage." (PMID 36311752, 2022). "However (4.3.2), during metabolic disorders caused by excess energy, the NLRP3 inflammasome is likely to be activated by aberrant lipid metabolites and/or high glucose levels, which subsequently results in the secretion of IL-18 as well as IL-1β, which can induce inflammatory responses." (PMID 30717382, 2019).
metabolic disorders (continued). "Therefore, we speculated that TRIM31 deficiency could facilitate NLRP3 inflammasome activation and then have an important role in the development of metabolic disorders." (PMID 29497383, 2018). "This aligns with previous research showing that the targeting of NLRP3 can alleviate liver damage in metabolic diseases." (PMID 41530833, 2026). "Here, we discuss the impact of NLRP3 on autoimmune diseases, metabolic disorders, neurological conditions, fibrosis, and tumors." (PMID 40830103, 2025). "Angiogenin-mediated tsRNAs regulate inflammation and metabolic disorders via targeting NLRP3 inflammasome." (PMID 39870617, 2025). "The current study is the first to demonstrate that ECG can improve metabolic disorder by inhibiting inflammatory responses and NLRP3 inflammasome activation as well as modulating the PI3K/AKT1 signaling pathway." (PMID 41169786, 2025). "TXNIP induces oxidative stress, inflammation, and pyroptosis through the activation of the NLRP3 inflammasome in metabolic disorders." (PMID 39629879, 2025). "Specifically, it can reduce macrophage infiltration and inflammatory cytokine production in the liver and adipose tissues, alleviating metabolic disorders in obese mice by inhibiting TLR3/NLRP3 (NLR family pyrin domain containing 3) inflammasome activation." (PMID 40863244, 2025). "Statins indirectly inhibit NLRP3 by reducing the cellular cholesterol load that otherwise triggers inflammasome activation in metabolic diseases." (PMID 41488670, 2025). "NLRP3’s role extends to metabolic disorders, and medicines that interact with NLRP3 have demonstrated a benefit in treating some BD symptoms." (PMID 39273641, 2024). "NLRP3 inflammasome activation plays an essential role in the development of metabolic diseases, including obesity and NAFLD, and can serve as a therapeutic target." (PMID 38067561, 2023). "The elevated intracellular cAMP levels can induce the phosphorylation and the ubiquitination of NLRP3 to block NLRP3-dependent inflammation and NLRP3-related metabolic disorders." (PMID 36899929, 2023). "In Nlrp−/− mice, reduced NLRP3-inflammasome activity inhibits liver damage, whereas inhibition of autophagy stimulates the NLRP3 inflammasome to promote inflammatory states and metabolic disorders." (PMID 37739179, 2023). "There are different pathways involved in the pathogenesis of metabolic diseases, and increased knowledge suggests a role of the activation of the NF-kB pathway and NLRP3 inflammasome as key mediators of metabolic inflammation." (PMID 37372020, 2023). "Defective mitogenesis leads to persistent and unresolved activation of the NLRP3 inflammasome, leading to autoinflammatory and metabolic disorders that exacerbate the development of metabolic diseases." (PMID 37926816, 2023). "Inflammatory cytokines mediated by NLRP3 can be activated in various cells in metabolic tissues and lead to metabolic disorders." (PMID 36834674, 2023). "Abnormal activation of NLRP3 inflammasome has been demonstrated to stimulate inflammatory or metabolic diseases." (PMID 36238294, 2022). "Complex nutraceutical programs have been confirmed to have preventive and therapeutic utility in a wide range of diseases in which NLRP3 inflammasome activity plays a mediating role, such as COVID-19, chronic kidney disease, and metabolic disorders." (PMID 36111168, 2022). "Taken together, our results demonstrate that KA protects against metabolic disorders via inhibition of the NLRP3 inflammasome." (PMID 36311752, 2022). "Recently, emerging studies have demonstrated that there is an interaction between autophagy and NLRP3 inflammasome, more importantly, the interaction plays a crucial role in metabolic diseases." (PMID 35309342, 2022). "Emerging evidence have shown that the interplay between autophagy and NLRP3 inflammasome plays a crucial role in metabolic diseases." (PMID 35309342, 2022).
metabolic disorders (continued). "In this review, the interplay between autophagy and the NLRP3 inflammasome and its mechanism are explored in metabolic disorders to provide ideas for the relevant basic research in the future." (PMID 33796528, 2021). "Nevertheless, this highlights PPARγ agonism as a therapeutic option for targeting NLRP3 inflammasome activation in NLRP3-related metabolic diseases." (PMID 33500734, 2021). "Several polyphenol compounds have been reported to have anti-inflammatory capacity and effects on the NLRP3 inflammasome in chronic and metabolic diseases." (PMID 34571975, 2021). "Specific inhibitors of NLRP3 inflammasome activation which can potentially be used to treat metabolic disorders are also discussed." (PMID 33435142, 2021). "For example, in metabolic disorders, does autophagy promote the activation of the NLRP3 inflammasome?" (PMID 33796528, 2021). "As a molecular switch of inflammatory reaction, NLRP3 is closely related to immune regulation, metabolic disorders, and inflammatory responses to various diseases." (PMID 34631209, 2021). "In this review, there are two mechanisms of the effects of autophagy on NLRP3 inflammasome in metabolic disorders: One is that autophagy suppresses NLRP3 inflammasome by inhibiting ROS production through scavenging damaged mitochondria." (PMID 33796528, 2021). "The NLRP3 inflammasome is probably activated by a high glucose concentration or abnormal lipid metabolites, which accompany metabolic disorders." (PMID 33546399, 2021). "In this review, we summarized the recent studies on the interplay between autophagy and NLRP3 inflammasome in metabolic disorders to provide ideas for the relevant basic research in the future." (PMID 33796528, 2021). "Abnormal activation of NLRP3 inflammasome can lead to a variety of diseases including metabolic diseases." (PMID 33796528, 2021). "NLRP3 inflammasome also participates in the occurrence and development of a variety of metabolic diseases as an important member." (PMID 34305953, 2021). "And are there any side effects of targeting autophagy/NLRP3 inflammasome to improve metabolic disorder?" (PMID 33796528, 2021). "The activation of NLRP3 is closely related to the occurrence and process of a variety of inflammatory and metabolic diseases." (PMID 34616481, 2021). "Rationale: Stimulation of the NLRP3 inflammasome by metabolic byproducts is known to result in inflammatory responses and metabolic diseases." (PMID 33500734, 2021). "In present study, we found that vaspin inhibited metabolic disorder-induced ER stress, autophagy impairment, disruption of lysosomal membrane integrity and subsequent NLRP3 inflammasome activation, and cell death in PTCs." (PMID 33742129, 2021). "3-TYP, a selective SIRT3 inhibitor, reversed AEDC effect on autophagy, indicating that AEDC inhibited NLRP3 inflammasome activation to ameliorate inflammation-related metabolic disorders by promoting autophagy via SIRT3." (PMID 33796528, 2021). "The interplay between autophagy and NLRP3 inflammasome plays an important role in metabolic disorders." (PMID 33796528, 2021). "Accordingly, to explore the specific mechanism and important role of NLRP3 in kidney injury induced by metabolic disorders will provide new ideas and directions for the prevention and treatment of metabolic-associated kidney diseases." (PMID 34305953, 2021). "NLRP3 inflammasome is overactivated in several neurodegenerative, cardiac, pulmonary, and metabolic diseases." (PMID 34202842, 2021). "These show the link between the NLRP3 inflammasome and metabolic diseases, suggesting how the metabolic dysfunction leads to augmented inflammation." (PMID 33603747, 2020). "The contribution of lncRNA GM15441 in regulating the NLRP3 inflammasome machinery in major metabolic disorders would be an interesting platform to explore." (PMID 33101288, 2020).
metabolic disorders (continued). "Previous studies have demonstrated that the NLRP3 inflammasome is a key mediator in the development of various metabolic diseases and host inflammatory responses." (PMID 33603747, 2020). "Glucose, fatty acids, and islet amyloid polypeptide activate the NLRP3 inflammasome driving to metabolic disorders, T2D, and secondary CMS by pancreatic islet inflammation and subsequent β-cell failure and destruction." (PMID 33172097, 2020). "The development of experimental models of neurological and psychiatric diseases, metabolic disorders, and chronic inflammatory diseases has allowed us to better understand the pathophysiological role of NLRP3 in these pathological conditions." (PMID 31200447, 2019). "Recent study have reported that HFD-induced NLRP3 inflammasome participated in inflammation and metabolic disorders." (PMID 34104129, 2019). "TGR5 signaling prevents metabolic disorder by inhibiting NLRP3 inflammasome in a manner dependent on cAMP-PKA." (PMID 31866999, 2019). "Inappropriate NLRP3 inflammasome activation can induce autoinflammatory, autoimmune, or metabolic disorders." (PMID 29868015, 2018). "Among the different inflammasomes, the NLRP3 inflammasome has been most studied because of its relevance to many metabolic diseases in humans." (PMID 29686531, 2018). "Our study demonstrates that inhibition of NLRP3‐dependent metainflammation by TR is efficient to reverse the metabolic disorders in diabetic mice." (PMID 29531021, 2018). "Recently, CY-09 has been reported to directly target NLRP3, inhibiting its activation in vivo and reversing metabolic disorders through inhibition of NLRP3-dependent IL-1β production in a mouse model of T2D." (PMID 30619282, 2018). "Our results would provide a novel preventive or therapeutic strategy using anti-inflammatory phytochemicals targeting NLRP3 inflammasome for the treatment of metabolic diseases such as acute gout." (PMID 27934918, 2016). "Diverse stimuli, including mitochondrial damage, have been shown to provoke the NLRP3 inflammasome during infection and metabolic diseases." (PMID 26498951, 2016). "This is in agreement with previous findings that neutrophil elastase KO mice have reduced levels of IL-1β in the liver and serum and that diminished NLRP3 inflammasome and caspase-1 activity elicits protection from high-fat diet mediated metabolic disorder." (PMID 26405763, 2015). "Here, we demonstrate a novel non‐classical action that endothelial Nlrp3 inflammasome activation promotes disruption of inter‐endothelial tight and adherens junction integrity in metabolic diseases." (PMID 26293846, 2015). "Taken together, these findings suggest that during the progression of many metabolic diseases, the accumulation of abnormal metabolic products activates the NLRP3 inflammasome." (PMID 26594174, 2015). "The present study provided new evidence to show the direct contribution of NLRP3 inflammasome in the pathogenesis of DCM, which was associated with the IL-1β-related metabolic disorder and caspase-1-mediated pyroptosis in myocardium." (PMID 25136835, 2014). "NLRP3 inflammasome-mediated production of mature IL-1β has been recently identified as a critical mediator in the disease progression of a variety of metabolic diseases." (PMID 25192391, 2014). "A large body of evidence places RIPK1/3-driven caspase-8 or MLKL signaling upstream of NLRP3 inflammasome activity in a range of disease settings, yet their contribution to inflammasome activity in metabolic disease is less clear." (PMID 39532538, 2025). "Mitochondrial dysfunction, marked by reactive oxygen species (ROS)-NOD-like receptor family pyrin domain-containing 3 (NLRP3) inflammasome activation and impaired sarco/endoplasmic reticulum calcium ATPase 2a (SERCA2a) stability, exacerbates metabolic disorder." (PMID 41256846, 2025).
metabolic disorders (continued). "This interrelationship suggests that modulating ALP activity may represent a novel therapeutic avenue to restrict NLRP3 inflammasome activation in both metabolic disorders and AD." (PMID 40589337, 2025). "Nevertheless, further research is needed to elucidate tissue- and cell-type-specific mechanisms, differences between canonical and non-canonical activation pathways, and relative contributions of central versus peripheral NLRP3 activity to systemic metabolic diseases." (PMID 40943225, 2025). "ROS are common signals that activate the NLRP3 inflammasome, and sugars, lipids, and amino acids can induce mitochondrial ROS accumulation to activate NLRP3 and induce pyroptosis, which contributes to disease progression in various metabolic diseases." (PMID 40996268, 2025). "NLRP3 inflammasome, as a multi-protein complex, can be activated by various damage- or pathogen-related molecular patterns, and the improper activation of NLRP3 inflammasome can lead to autoinflammatory, autoimmune, or metabolic disorders." (PMID 38667787, 2024). "NLRP3 inflammasomes are multimeric cytoplasmic protein complexes composed of the sensor protein NLRP3 linked to ASC and caspase-1, which are closely associated with oncological and metabolic diseases." (PMID 36865551, 2023). "Given the importance of the NLRP3 inflammasome in metabolic diseases, assessing the relationship between vitamin D and this inflammatory complex may have therapeutic implications." (PMID 38276294, 2023). "Nlrp3−/− mice were resistant to HFD-induced metabolic disorders." (PMID 36311752, 2022). "The NLRP3 inflammasome contributes to the progression of metabolic disorders." (PMID 36311752, 2022). "Moreover, incorrect induction of NLRP3 inflammasome has been reported to stimulate inflammatory or metabolic diseases." (PMID 36238294, 2022). "Thus, KA ameliorated inflammation and metabolic disorders by blocking calcium mobilization-mediated NLRP3 inflammasome activation via GPR35." (PMID 36311752, 2022). "A variety of metabolic disorders leads to the activation of NLRP3 inflammasome in the kidney." (PMID 34305953, 2021). "Recently, more and more studies have shown that there is an interplay between autophagy and NLRP3 inflammasome in macrophage and the interplay plays an important role in many diseases including metabolic diseases, the mechanism of which remains to be elucidated." (PMID 33796528, 2021). "Additionally, ER stress and the NLRP3 inflammasome exert an important role in metabolic diseases induced by a high-fat diet." (PMID 34760017, 2021). "The NLRP3 inflammasome is a cytosolic molecular complex whose expression in AT directly correlates with body weight and aging, while its inactivation significantly mitigates metabolic disorders." (PMID 33809891, 2021). "Currently, the well-established mechanisms for the NLRP3 inflammasome activation include intracellular ion flux (such as K+ efflux, Ca2+ flux, Na+ flux and Cl− efflux), mitochondrial damage, Golgi disassembly, lysosomal disruption and metabolic disorder." (PMID 34639204, 2021). "NLRP3 inflammasome is the sensor of the innate immune system that initiates inflammatory response to stimulations, and participates in the occurrence and development of various metabolic diseases and kidney injury." (PMID 34305953, 2021). "The inflammation from NLRP3 inflammasome activation plays a crucial role in many metabolic diseases including NAFLD, and our animal experiments showed that Man inhibits NLRP3-mediated inflammation and pyroptosis in hepatocytes by western blot and RNA-seq analysis." (PMID 34734090, 2021). "This forms the basis why new drug candidates, such as natural polyphenols, which prevent IL-1β secretion by inhibiting the function of NLRP3 or other inflammasome components, have lately been under scrutiny in relation to immunological, neurological, and metabolic diseases." (PMID 34062977, 2021).